IL10 (interleukin 10)
Diseases named in the same sentence as IL10 in open-access papers (continued):
Sharing a sentence is not in itself a finding about the gene and the disease.
Neonatal sepsis (23 papers, 2013 to 2026). Systemic inflammatory response to infection in newborn babies. "(i) It is an innovative study that directs the spotlight onto the effect of the presence of TLR2, TLR4, IL6, and IL10 polymorphisms in the context of early neonatal sepsis in preterm neonates." (PMID 41598258, 2026). "Previous studies have demonstrated that cytokines such as IL-6, IL-8, IL-10, and IL-27 were biomarkers of neonatal sepsis and their diagnostic properties have been investigated." (PMID 38027268, 2023). "The diagnostic validity of IL-6, IL-8, IL-10 and IL-27 for neonatal sepsis were investigated in several cross-sectional studies and meta-analyses." (PMID 38027268, 2023). "Furthermore, the meta-analysis results suggest a significantly increased risk of neonatal sepsis with the AA+GA, AA genotype of the IL-10-1082 G/A polymorphism in six genetic models and the A allele, AA genotype of TNF-α-308G/A (rs1800629) polymorphism." (PMID 38848433, 2024). "Moreover, the results showed that the OR value of the IL-10-1082 G/A polymorphism merged in the dominant gene model was statistically significant (P = 0.016), indicating a significant increase in the risk of neonatal sepsis with the AA+GA genotype (OR = 1.731, 95% CI: 1.108–2.705)." (PMID 38848433, 2024). "Notably, TLR2-dependent IL-10 production was shown to impair immune cell recruitment to infected tissues during GBS neonatal sepsis and neonatal mice deficient in TLR2 exhibited reduced levels of IL-10 upon GBS infection that were ultimately associated with bacterial clearance." (PMID 37747229, 2023). "Similarly, a high IL-10/TNF ratio has also been associated with severe late-onset neonatal sepsis." (PMID 25614712, 2014). "Elevated serum levels of several pro-inflammatory cytokines—such as IL-6, IL-8, IL-10, IL-1β, TNF-α, and MCP-1—have been associated with neonatal sepsis." (PMID 40948499, 2025). "Interleukin-10 (IL-10) has anti-inflammatory and immunomodulatory effects and plays a significant regulatory role in the occurrence, development, and outcome of neonatal sepsis." (PMID 38848433, 2024). "Interleukins including IL-6, IL-8, IL-10, and IL-27 demonstrated favorable performance in the detection of neonatal sepsis." (PMID 38027268, 2023). "Superiority index of IL-8, IL-10, and IL-27 were 1.84 (0.20, 5.00), 1.04 (0.20, 5.00), and 2.21 (0.20, 5.00) in the detection of late-onset neonatal sepsis." (PMID 38027268, 2023). "Results of ANOVA model revealed that the superiority index of IL-6, IL-8, IL-10, and IL-27 were 1.20 (0.14, 5.00), 5.14 (0.33, 7.00), 0.75 (0.14, 5.00), and 1.31 (0.14, 5.00) in the detection of early-onset neonatal sepsis." (PMID 38027268, 2023). "In this study, we evaluated the diagnostic and prognostic accuracy of transcriptional (CX3CR1, CD74) and proteic (IL6, IL10, IP-10, PCT) biomarkers and their association with clinics and maternal risk factors for neonatal sepsis." (PMID 36509812, 2022). "Accuracy of transcriptional (CD74, CX3CR1), proteic (PCT, IL-6, IL-10, IP-10) biomarkers and clinical characteristics to diagnose and prognose neonatal sepsis were measured." (PMID 36509812, 2022). "In this study, we evaluated the diagnostic value of salivary IL-10 as a noninvasive marker as well as serum IL-10, CRP, MPV, and CRP/MPV ratio in early diagnosis of late-onset neonatal sepsis in full-term neonates." (PMID 34676267, 2021). "Other studies showed that the optimal cutoff value of IL-10 in the diagnosis of neonatal sepsis ranged from 3.8 to 49 pg/ml." (PMID 34676267, 2021). "We aimed to investigate the diagnostic role of salivary and serum interleukin 10 (IL-10), C-reactive protein (CRP), mean platelet volume (MPV), and CRP/MPV ratio in the diagnosis of late-onset neonatal sepsis in full-term neonates." (PMID 34676267, 2021).
Neonatal sepsis (continued). "Among IL-6, IL-8, and IL-10, both IL-6 and IL-8 were found to predict neonatal sepsis at cutoffs of 10.85 pg/mL (sensitivity: 92.5%; specificity: 97.6%) and 60.05 pg/mL (sensitivity: 93.7%; specificity: 65%), respectively." (PMID 28487810, 2017). "In the present study, serum levels of the proinflammatory cytokines TNF-α, IL1-β, and IL-6 and the anti-inflammatory cytokines IL-4 and IL-10 were evaluated for 25 subjects with neonatal sepsis." (PMID 28367457, 2017). "In an earlier study, IL-10 was reported to be highly sensitive and specific in the diagnosis of neonatal sepsis." (PMID 28367457, 2017). "Findings of this network meta-analysis suggest that interleukins including IL-6, IL-8, IL-10, and IL-27 may have favorable performance in the detection of neonatal sepsis." (PMID 38027268, 2023). "IL-10, together with IL-6 and IL-8, are initial markers with high specificity for neonatal sepsis." (PMID 33659006, 2021). "Furthermore, the expression level of IL-10 was positively correlated with the severity of neonatal sepsis." (PMID 34676267, 2021). "Suppressing pro-inflammatory cytokines such as TNF and/or enhancing endogenous IL-10 production might therefore be beneficial in neonatal sepsis." (PMID 33072121, 2020). "Noteworthy, IL-6 and IL-10 have also been recommended as indicators of neonatal sepsis and increased levels of IL-6 and TNFα in vaginal secretions of women with preterm premature rupture of membranes were good predictors of fetal inflammatory response syndrome." (PMID 33396944, 2020). "Neonatal MΦ-0, MΦ-IFNy and MΦ-IL10 polarisation is impaired with respect to phenotype and functions tested which may contribute to sustained inflammation in neonatal sepsis." (PMID 31953452, 2020). "As evidenced by these studies, IL-6, IL-8, and IL-10 may be the most promising cytokine biomarkers to diagnose neonatal sepsis once more narrow ranges in cutoffs across studies are established." (PMID 28487810, 2017). "Therefore, IL-10 plays an important role in the early diagnosis of late-onset neonatal sepsis." (PMID 34676267, 2021). "Since neonatal sepsis is often followed by inflammatory organ damage, and since local tissue MΦ are extremely difficult to obtain, we decided to polarise monocyte-derived macrophages by preconditioning with M-CSF and additional treatment with either IFNy, or IL10." (PMID 31953452, 2020). "IL-6 and IL-12/23p40 are other cytokines that go together with IL-8, IL-10, and TNF-α as biomarkers of prenatal and postnatal inflammation and neonatal sepsis." (PMID 36768650, 2023). "GNT treatment decreased LPS-induced elevation of TNF-α, IL-2, and IL-1β expression levels and increased LPS-induced elevation of IL-10 expression levels in the peritoneal fluid, indicating the anti-inflammatory effect of GNT in neonatal sepsis." (PMID 36162982, 2022). "To evaluate the association of CRP and inflammatory cytokines in the context of neonatal sepsis, we conducted correlation analysis between CRP and the cytokines TNF-α, IL-6, and IL-10." (PMID 28367457, 2017). "First, the cytokines IL-6, TNF, and IL-10 have been found in many studies to be significantly elevated in human infants experiencing LOS, as well as other mouse models of neonatal sepsis." (PMID 40557325, 2025). "Notably, S100A9 was reported to regulate the intestinal environment: Mice lacking S100A9 displayed reduced CX3CR1 protein levels, IL10 and TGF mRNA expression, and fewer T‐reg cells in intestinal tissues, accompanied by a higher risk of fatal neonatal sepsis." (PMID 41542228, 2026).
nosocomial infection (23 papers, 2010 to 2025). An infection acquired in a hospital or other healthcare setting. "In this study, the data suggest that occurrence of nosocomial infection in CCI is associated with increased IL-10 and IL-15 levels in the circulation." (PMID 38426112, 2024). "Persisting high IL-10 concentration was associated with subsequent nosocomial infection, suggesting its possible interest in immune monitoring of most severe patients." (PMID 37365194, 2023). "In the SM group, IL-10 elevation persisting from admission to day 2 was significantly associated with subsequent nosocomial infection." (PMID 37365194, 2023). "Enhanced IL-10 signaling has been associated with the development of nosocomial infection in at least one study." (PMID 30459764, 2018). "Though IL-10 has direct immunosuppressive effects, its association with development of nosocomial infection is less straight forward." (PMID 30459764, 2018). "In association with measurements of interleukin-10 (IL-10) in the plasma, HLA-DR levels can predict outcomes after nosocomial infections." (PMID 20385017, 2010). "IL‐10, an anti‐inflammatory cytokine, can play a contextual role where lower levels initially can enhance survival through the promotion of infection control, while prolonged IL‐10 deficiencies can result in susceptibility to nosocomial infections and immunosuppression." (PMID 38193117, 2024). "Whether monitoring the potent anti-inflammatory cytokine IL-10 helps to identify patients at high risk for developing nosocomial infection deserves further investigation." (PMID 37365194, 2023). "Higher IL-10 levels may be associated with worse immune dysfunction and greater susceptibility to nosocomial infections." (PMID 37365194, 2023). "Importantly, increased expressions were associated with increased occurrence of secondary nosocomial infections and mortality after septic shock as well as with decreased mitogen-induced lymphocyte proliferation and increased circulating IL-10 concentration." (PMID 21418617, 2011). "In our group with SM, patients with high IL-10 levels during the first 3 ICU days had a significantly greater number of nosocomial infections." (PMID 37365194, 2023). "Our data showing elevated systemic IL-10 levels following SAH are consistent with the existing evidence in literature and explore novel findings on elevated IL-10 and occurrence of nosocomial infections following SAH." (PMID 32106601, 2020). "The remaining transcriptomic candidates of the heme degradation pathway (HP, CD163, HMOX1; IL-10) and IL-8 clustered together, with moderate correlation to nosocomial infections (lower half of the heatmap)." (PMID 26607226, 2015). "Early plasma levels of the antiinflammatory cytokine, IL-10, were significantly higher in patients who went on to develop persistent or nosocomial infection." (PMID 25005517, 2014). "Interestingly, the same monocytes are capable of secreting significant levels of anti-inflammatory mediators, such as IL-1 receptor antagonist and IL-10, which correlate with increased rates of nosocomial infection and higher mortality." (PMID 39720718, 2024). "In this retrospective study, the high levels of IL-6 and IL-10 in non-survivors were measured, and we identified that the nosocomial infection after PICU admission was an independent risk factors for all-cause hospital mortality." (PMID 32772917, 2020). "This indicated that high levels of IL-6 and IL-10 in non-survivors could provide an insight for adenovirus-associated nosocomial infection." (PMID 32772917, 2020). "For example, it is well-established that IL-6, IL-8, IL-10, and MCP-1 (CCL2) are elevated early after injury and are correlated with adverse outcomes including nosocomial infection, multiple organ dysfunction syndrome, and mortality." (PMID 36532045, 2022). "There was a significant elevation in serum IL-10 levels on day 7 in SAH patients who developed cerebral vasospasm (CVS), nosocomial infections or shunt-dependent chronic hydrocephalus." (PMID 32106601, 2020).
nosocomial infection (continued). "In addition, the circulating levels of five cytokines, IL-10, IL-15, IL-6, IL-8, and TNF alpha, were measured for each patient, and the results showed that patients with nosocomial infection had significantly increased IL-10 levels at RCC admission." (PMID 38426112, 2024). "A recent study reported decreased T-cell ex vivo PHA-induced production of IFNγ, IL-2 and IL-10 in children with septic shock that went on to develop persistent or nosocomial infection compared with septic shock children who did not." (PMID 27015534, 2016). "Interestingly, high IL-10 levels persisting over the 3 days were more common in patients with versus without nosocomial infections." (PMID 37365194, 2023). "Among septic shock children, those who went on to develop persistent or nosocomial infection had decreased T-cell ex vivo PHA-induced production of IFN-γ (P = 0.01), IL-2 (P = 0.01), IL-4 (P = 0.008), and IL-10 (P = 0.001) compared with septic shock children who did not." (PMID 25005517, 2014).
acne (22 papers, 2014 to 2025). An inflammatory process of the sebaceous glands which is characterized by comedones, nodules, papules and/or pustules on the skin. "Our findings suggest a causal relationship between high levels of MIP-1A/IL-10 and a reduced risk of acne." (PMID 38115273, 2023). "Our study found that high levels of circulating IL-10 were associated with a reduced risk of acne (OR = 0.799, 95% CI = 0.641–0.995, P = .045 per 1 SD increase)." (PMID 38115273, 2023). "Our study conclusively identified a causal relationship between il-10 and circulating levels of acne risk and a suggestive link between MIP-1A and SCGF-β and acne." (PMID 38115273, 2023). "Furthermore, W. viridescens UCO-SMC3 has been demonstrated to possess immunomodulatory effects via the upregulation of the interleukin-10 (IL-10) pathway, thereby alleviating inflammation associated with acne." (PMID 40362894, 2025). "Different strains of C. acnes can induce varying immune responses; acne-associated strains trigger pro-inflammatory cytokines like IFNγ and IL-17, whereas health-associated strains promote the production of anti-inflammatory IL-10." (PMID 38791344, 2024). "Furthermore, skin health-associated type II and III lineages and neutral subset 1 strains induced 2-to-4 times higher levels of anti-inflammatory IL-10 compared to acne-associated strains and neutral subset 2 strains." (PMID 31086023, 2019). "GATA6 expressed in differentiating sebocytes can induce the expression of IL-10 and negatively regulates acne-driven IL-8 and IL-17 cytokines." (PMID 38357543, 2024). "In contrast, the secretion of anti-inflammatory IL-10 by the PBMCs of acne patients significantly decreases." (PMID 37894244, 2023). "Our study conclusively identified a causal relationship between IL-10 and circulating levels of acne risk, as well as a suggestive link between MIP-1A and SCGF-β and acne." (PMID 38115273, 2023). "In the Finnish cohort, the expression of Foxp3, TGF-β and IL-10 were found significantly up-regulated in acne lesions by RT-PCR, and the latter two were at higher levels in acne lesions compared with psoriatic lesions." (PMID 25153527, 2014). "In the German cohort, TGF-β and IL-10 displayed a slightly enhanced expression in acne lesions and also the expression of Foxp3 was detected." (PMID 25153527, 2014). "Elevated serum levels of anti-inflammatory cytokine IL-10 are found in acne patients and the expression of IL-10 is increased in acne lesions." (PMID 25153527, 2014). "Oral probiotics have been found to elevate anti-inflammatory IL-10 levels in individuals with acne." (PMID 38791344, 2024). "Furthermore, the capability of CD14 cells in acne patients to engulf P. acnes bacteria is impaired, but the introduction of exogenous IL-10 to PBMC cultures can reinstate phagocytic activity." (PMID 37894244, 2023). "The increased IL-10 expression and Treg cells may demarcate the inflammation of a single acne lesion efficiently." (PMID 35329904, 2022). "Moreover, elevated serum levels of IL-10 were found in acne patients, and the expression of this cytokine was increased in acne lesions." (PMID 35329904, 2022). "The increased IL-10 expression and Tregs may demarcate the inflammation of a single acne lesion efficiently from the beginning." (PMID 25153527, 2014). "Therefore, in order to understand the expression of inflammation in the acne model, we selected the pro-inflammatory cytokine IL-1β, MMP-2, and the anti-inflammatory cytokine IL-10 as the detection indicators in this experiment to observe their expression levels in the acne inflammation model." (PMID 40520168, 2025). "Another study has shown that in addition to inhibiting the synthesis of IL-1β and other pro-inflammatory factors, IL-10 can also promote the production of tissue inhibitors of matrix metalloproteinases (TIMPs), thereby inhibiting the expression of MMPs and reducing scar formation in acne." (PMID 40520168, 2025).
acne (continued). "On the other side, in the Jurkat cell type, SLST H1 EVs and 50 μg/mL dose of SLST H2 EVs induced a significant expression of the anti-inflammatory cytokine IL-10, reinforcing the possible protective role of these two non-pathogenic strains during acne vulgaris development." (PMID 37749255, 2023). "Therefore, the genus Fusicatenibacter may play a protective role in acne through the secretion of IL-10." (PMID 37894244, 2023). "The acne-related C. acnes subtypes increase secretion of IFN-γ and IL-17, while decreasing levels of IL-10 in PBMCs." (PMID 38357543, 2024). "Significantly increased expression of TLR-4, IL-2, IL-10, and TIMP-2 and decreased MMP-9 havebeen demonstrated in patients with acne prone to scarring." (PMID 38398480, 2024). "In agreement with published literature, acne-derived strains (C-type strains HL096PA1, HL043PA1, and HL005PA1) induced greater levels of IL-10 and IFN-γ from human monocyte-derived dendritic cells than health-associated K-type strains HL110PA3, HL110PA4, and HL042PA3." (PMID 37478901, 2024). "We believe that IL-10, MIP-1A and SCGF-β could be potential therapeutic targets for acne development." (PMID 38115273, 2023). "Except for IL-10, SCGF-β, and MIF-α, other cytokines (e.g., VEGF, GRO-α, Trail, MIG, IL-7, IL-17) did not exhibit any association with acne risk in the IVW primary MR analysis or other secondary analyses." (PMID 38115273, 2023). "Moreover, the increased expression of cytokines and other inflammatory markers such as IL-1α, beta-defensins 1 and 2, TNF-α, IL-1β, IL-8, IL-10, matrix metalloproteinases MMP-1, MMP-3, MMP-9, CXCL-2 was found in acne lesions in vivo." (PMID 25153527, 2014). "In acne-induced PS formation, the expression of anti-inflammatory cytokines such as IL-10 decreases and the expression of proinflammatory cytokines such as TNF-α increases; these factors have been shown to play crucial roles in the development of acne-induced PSs." (PMID 38585341, 2024). "Of note, TLR2 recognition of Candida albicans suppresses inflammatory responses via production of IL-10 and enhanced Treg survival but it is not known if TLR2 recognition in acne has the same consequences." (PMID 25153527, 2014).